ACP2 (acid phosphatase 2, lysosomal)
Description:
Lysosomal acid phosphatase that catalyzes the hydrolysis of orthophosphoric monoesters to alcohols and phosphate under acidic conditions (Probable). May contribute to the removal of mannose-6-phosphate (Man6P) from lysosomal proteins after their delivery to lysosomes, acting in concert with ACP5 (By similarity). (Microbial infection) Plays a crucial role in the membrane fusion step of the influenza A and B viruses entry process.
Synonyms: LAP
Tractability: Antibody: UniProt predicts a signal peptide or a membrane-spanning region. PROTAC: ubiquitination databases record sites on it; its protein half-life has been measured.
Gene: Protein-coding gene on chromosome 11 (47,238,400 to 47,249,288, reverse strand). Ensembl gene ENSG00000134575.
Subcellular location: Lysosome membrane; Lysosome lumen
Gene Ontology:
Molecular function: acid phosphatase activity; protein binding
Biological process: regulation of viral entry into host cell; lysosome organization
Cellular component: extracellular exosome; lysosomal lumen; lysosomal membrane; lysosome; membrane
Genetic constraint (gnomAD): Loss-of-function variants: 33 observed, 54.87 expected, observed/expected ratio (o/e) 0.6, 90% interval 0.46 to 0.8. The upper end of that interval is the gene's LOEUF score, 0.8, which puts it in group 3 of 6, group 1 being the genes least tolerant of losing a copy. Missense variants: 474 observed, 560.91 expected, observed/expected ratio (o/e) 0.85, 90% interval 0.78 to 0.91. Synonymous variants: 201 observed, 222.03 expected, observed/expected ratio (o/e) 0.91, 90% interval 0.81 to 1.02.
Homologues: Orthologues: chimpanzee ACP2 (99% identical), macaque ACP2 (99% identical), dog ACP2 (95% identical), pig ACP2 (94% identical), rabbit ACP2 (93% identical), guinea pig ACP2 (93% identical), rat Acp2 (90% identical), mouse Acp2 (89% identical), tropical clawed frog acp2 (60% identical), zebrafish acp2 (50% identical), Drosophila melanogaster Acph-1 (34% identical), Caenorhabditis elegans pho-5 (31% identical), and 14 more. Paralogues in human: ACP4 (44% identical), ACP3 (43% identical), ACP6 (26% identical), PXYLP1 (21% identical), FRA10AC1 (9% identical).
Diseases named in the same sentence as ACP2 in open-access papers:
ACP2 is named in the same sentence as 31 diseases in open-access papers, as found by Europe PMC text mining. Sharing a sentence is not in itself a finding about the gene and the disease. The quoted sentences say what the papers report.
Ataxia (4 papers, 2016 to 2021). Ataxia refers to impaired coordination of voluntary muscle movement. "An Acp2 mutant mouse called nax (naked and ataxia), resulting from a spontaneous point mutation in the Acp2 gene, exhibits an overall impairment of cerebellar cortex development and severe defects in cerebellar function." (PMID 33804256, 2021). "Perturbation of murine Acp2 causes lysosomal storage deficits, kyphoscoliosis, cerebellar abnormalities, and ataxia." (PMID 30108311, 2020). "Spontaneous mutation in the lysosomal acid phosphatase 2 (Acp2) mouse (nax—naked-ataxia mutant mouse) correlates with severe cerebellar defects including ataxia, reduced size and abnormal lobulation as well as Purkinje cell (Pc) degeneration." (PMID 26784182, 2016). "Lysosomal acid phosphatase 2 (Acp2) mutant mice (naked-ataxia, nax) have a severe cerebellar cortex defect with a striking reduction in the number of granule cells." (PMID 33804256, 2021). "For this purpose, Acp2 (acid phosphatase 2, lysosomal) mutant mice (aka; nax, naked and ataxia) exhibiting excessive PCs migration were examined and the transcription of Ncam1 was evaluated." (PMID 35126044, 2021). "We analyzed the Acp2 mutant mouse (nax: naked and ataxia), which displays excessive PC migration into the molecular layer, and investigated how the excessive migration of PCs along Bergmann glia could correlate to NCAM1 expression pattern in early postnatal days." (PMID 35126044, 2021).
diabetes (2 papers, 2017 to 2021). "We further made multivariate regression analysis using age, sex, hypertension, diabetes and ACP2 or PLD3 as covariates respectively." (PMID 34447787, 2021). "Besides confirming functional relevance of previously reported candidate genes with diabetes, SMR analysis also identified several novel candidate genes for diabetes, such as MRPL33, ACP2, and NR1H3." (PMID 28744461, 2017).
juvenile neuronal ceroid lipofuscinosis (2 papers, 2014 to 2016). A genetically heterogeneous group of neuronal ceroid lipofuscinoses (NCLs) typically characterized by onset at early school age with vision loss due to retinopathy, seizures and the decline of mental and motor capacities. "In particular, ACP2 has been associated with progressive supranuclear palsy and ACP2 activity levels are known to be increased in juvenile neuronal ceroid lipofuscinosis, a disease caused by mutations in the lysosomal protein CLN3 (Batten disease:)." (PMID 24722417, 2014).
asthma (1 paper, 2015). "It was hypothesized that the identified downregulation of M6PR, TPP1, GLB1, NEU1, ACP2, LAMP1 and HGSNAT leads to disorders of lysosome function, which results in asthma by causing T-cell dysfunction." (PMID 25633562, 2015).
Astigmatism (1 paper, 2022). A type of refraction error associated with abnormal curvatures on the anterior and/or posterior surface of the cornea. "To date, the known genes and candidate genes associated with astigmatism are PDGFRA, CLDN7, ACP2, and TNFAIP8L, of which PDGFRA has been shown to increase the risk of astigmatism 1.12 times." (PMID 35885949, 2022).
atopic asthma (1 paper, 2015). An asthma that is characterized by symptoms that are triggered by an allergic reaction caused by inhaled allergens such as dust mite allergen, pet dander, pollen and mold. "Among the genes identified in the present study (M6PR, TPP1, GLB1, NEU1, ACP2, LAMP1 and HGSNAT) that were significantly associated with lysosomal function, only TPP1 has been confirmed as being associated with atopic asthma." (PMID 25633562, 2015).
colon cancer (1 paper, 2017). "To examine whether this was because the expression of ACP2 induced chemosensitivity, we used the shACP2 lentivirus to knock down ACP2 expression in human CRC cell lines HCT-116 and DLD1 after we examined the expression level of ACP2 in six colon cancer cell lines." (PMID 28076332, 2017).
influenza (1 paper, 2017). An acute viral infection of the respiratory tract, occurring in isolated cases, in epidemics, or in pandemics; it is caused by serologically different strains of viruses (influenzaviruses) designated A, B, and C, has a 3-day incubation period, and usually lasts for 3 to 10 days. "This is the first report of the necessity of the host cellular factor ACP2 in influenza virus entry, and suggests that ACP2 may be an attractive target for the development of pan-influenza therapeutics." (PMID 28272419, 2017).
kidney damage (1 paper, 2024). "We confirmed the influence of several known NEMG on kidney disease and function and found novel associations for SLC39A13, CFL1, ACP2 or ATP5G1 with serum variables and kidney damage, and for SLC4A1, NUP210 and MYH14 with ESKD." (PMID 38858654, 2024). "Among the NEMG predictive of kidney damage along with serum phenotypes in our patients (NOS3, ACP2 and SLC39A13), some of them have previously been linked to kidney disease." (PMID 38858654, 2024).
medulloblastoma (1 paper, 2021). A malignant, invasive embryonal neoplasm arising from the cerebellum. "Our observations may pave the way for pharmacologic manipulation of Acp2 as an approach of cerebellar developmental disorders such as the SHH group of medulloblastomas and Group 3 tumors and MYC signaling." (PMID 33804256, 2021).
Obesity (1 paper, 2021). Accumulation of substantial excess body fat. "Finally, using the METSIM cohort, we found that the expression of the human ortholog of pho-1, ACP2, positively correlates with body weight and total triglycerides, which is in line with our observations showing that knockdown of C. elegans’s pho-1 prevents diet-induced obesity." (PMID 34492009, 2021).
tumor (3 papers, 2017 to 2018). "ACP2 expression was found increased significantly in tumors as compared with non-tumor colon tissues (p < 0.0001)." (PMID 28076332, 2017). "We first examined 76 sets of matched samples from primary CRC tumors and non-tumor colon tissues to be sure of the expression pattern of ACP2." (PMID 28076332, 2017). "Importantly, CETV prove tumor growth of ACP2 PDX as it significantly increases in longitudinal follow-up of 110 days." (PMID 29795641, 2018). "The present findings bolster the high expression of ACP2 in tumor cells, which may link to cell fate." (PMID 28076332, 2017). "This accords with significantly increased ADC values in ACP2 derived xenografts relative to ACP1 and ACP3 PDX, and higher average vital tumor content." (PMID 29795641, 2018).
cancer (2 papers, 2017 to 2023). A tumor composed of atypical neoplastic, often pleomorphic cells that invade other tissues. "The univariate and multivariate Cox proportional hazards analyses further illustrated the association of ACP2 expression with cancer mortality." (PMID 28076332, 2017).
infection (1 paper, 2017). The state of being infected such as from the introduction of a foreign agent such as serum, vaccine, antigenic substance or organism. "Depletion of ACP2 significantly reduced fusion following infection with B/Florida/4/2006." (PMID 28272419, 2017).
neurodegenerative disease (1 paper, 2020). A disorder of the central nervous system characterized by gradual and progressive loss of neural tissue and neurologic function. "ACP2 has known or suspected roles in several neurodevelopmental disorders, as emphasized by mutations in Acp2 causing severe cerebellar and neurodegenerative diseases." (PMID 33115496, 2020).
psychiatric disorder (1 paper, 2020). A disorder characterized by behavioral and/or psychological abnormalities, often accompanied by physical symptoms. "Integrated analysis of GWAS and expression data identified ACP2 as a loci related to prepulse inhibition, a measure of sensorimotor gating that is known to be affected in several psychiatric disorders." (PMID 33115496, 2020).
ACP2 also shares sentences with these, for which no sentence is quoted: Buruli ulcer (1 paper); Cognitive impairment (1); Hypertension (1); ischemic stroke (1); Jaundice (1); kidney disease (1); Kyphoscoliosis (1); lysosomal storage disorders (1); mucolipidosis (1); neurodevelopmental disorder (1); neurological disorders (1); Parkinsonism (1); progressive supranuclear palsy (1); serous ovarian cancer (1); Stroke (1).